MSN (moesin)
Diseases named in the same sentence as MSN in open-access papers (continued):
Sharing a sentence is not in itself a finding about the gene and the disease.
cancer (94 papers, 2008 to 2026). A tumor composed of atypical neoplastic, often pleomorphic cells that invade other tissues. "A panel of Clathrin Heavy Chain (CLTC), Ezrin (EZR), Talin-1 (TLN1), Adenylyl cyclase-associated protein 1 (CAP1), and Moesin (MSN) positive exosomes demonstrated 0.94–0.99 accuracy against other cancers." (PMID 40363817, 2025). "Higher MSN mRNA expression was also significantly associated with unfavorable survival in various types of human cancers, including lung, stomach, and pancreatic cancer in The Cancer Genome Atlas (TCGA) dataset." (PMID 32326232, 2020). "For example, we found a cancer-related D695Y mutation in the tumour suppressor Breast cancer type 1 susceptibility protein (BRCA1) that creates novel binding sites for the Yx[FILV]-binding FERM domains of Moesin (MSN) and Radixin (RDX)." (PMID 39009827, 2024). "In two separately constructed networks from postmortem brain tissue from patients with sporadic Alzheimer’s disease and tau transgenic mice at three stages of disease, we identified Moesin as a hub gene within an expression module associated with cancer and EMT." (PMID 36879821, 2023). "Since cell adhesion activity is linked to cancer progression and MSN connects the cell membrane and actin-based cytoskeleton, we investigated whether MSN influences cell adhesion activity." (PMID 37446127, 2023). "Moesin has been associated with formation of filopodia, which are dynamic actin-rich membrane protrusions important for cell adhesion, membrane trafficking (including EV internalisation), and therefore also of importance in cancer cell adhesion and invasion." (PMID 33573274, 2021). "Like the other two ERM proteins, expression of moesin is also linked to cancer progression." (PMID 33171868, 2020). "Moesin has been associated with filopodia formation, which are dynamic actin-rich membrane protrusions important for cell adhesion, membrane trafficking (including EV internalisation) and therefore also of importance in cancer cell adhesion and invasion." (PMID 32098295, 2020). "Three of these non-synonymous mutations modified known cancer genes (MSN, NRK, GPR112)." (PMID 25175524, 2014). "First, sphere formation assays and ALDH activity measurements were conducted based on varying levels of MSN expression to prove the connection of MSN to cancer stemness." (PMID 40696387, 2025). "Our findings uncover the critical role of MSN in regulating STAT3-mediated cancer stemness via the IL-6/NF-κB signaling axis." (PMID 40696387, 2025). "FN1 and MSN are aberrantly expressed in cancer cells and play a role in maintaining their epithelial character." (PMID 38421619, 2024). "Consistent with links between the blue module and cancer, we find that many blue module hub genes, such as Moesin (MSN), YAP1, TEAD1, and WWTR1 are well known for their role in cancer and mediate the EMT." (PMID 36879821, 2023). "High-level expression of Moesin is predominantly regulated at the posttranslational level in many cancers." (PMID 37736741, 2023). "Paradoxically, CM was enriched with PABPC1, ENO1, and MSN, all of which have been considered oncogenic since their elevated transcript levels in cancer tissues significantly reduce the survival rate." (PMID 36923539, 2023). "In cancer cells, the concomitant overexpression of HER2 and loss of moesin expression contributes to HER2 activation, which can be reverted with the use of moesin‐mimicking compounds." (PMID 36912768, 2023). "Here, we found that MAP4K4, in the collective context, also induces focal adhesion turnover predominantly through moesin phosphorylation in A431 carcinoma cells." (PMID 37369604, 2023). "While some functional redundancy exists among ERM proteins, studies have highlighted distinct but complementary roles for ERMs in regulating the same cellular processes, such as ezrin and moesin in cancer cell invasion." (PMID 36923551, 2022).
cancer (continued). "ERM proteins (Ezrin, Radixin, Moesin) are known to provide a physical connection between actin cytoskeleton and plasma membrane, thereby participating in cell migration and cancer metastasis." (PMID 36175399, 2022). "In previous studies, PAD inhibitors were furthermore found to affect cancer cell invasion proteins including moesin, which is a critical factor for cell migration and filopodia formation." (PMID 33573274, 2021). "In conclusion, we found that in LUAD, the expression of moesin in cancer tissues was significantly lower than that in normal tissues, and this phenomenon was strongly correlated with the poor prognosis of patients." (PMID 33838692, 2021). "While PAD2 inhibitor, followed by PAD3 inhibitor, had most effects on reducing cancer cell invasion, elevating moesin expression, and modulating EV signatures, PAD4 inhibitor had negligible effects and pan-PAD inhibitor Cl-amidine was also less effective." (PMID 33573274, 2021). "Another study also pointed out that reducing the expression of moesin can increase the accumulation of methotrexate in cancer cells." (PMID 33838692, 2021). "In the recent past, the role of FAK, Paxillin, and Moesin in relationship with sex steroids in the biology of normal and cancer cells has been the subject of extensive investigation." (PMID 30013514, 2018). "Proteins in the ezrin–radixin–moesin (ERM) family have been widely studied as regulators of cancer progression-related signaling that are involved in cell adhesion, migration, and polarity." (PMID 29085362, 2017). "Moesin, a member of the ERM (moesin, radixin, ezrin) family of proteins has been reported to be overexpressed in many kinds of cancers." (PMID 26846339, 2016). "Among the molecular mediators of cancer cell migration and invasion, moesin is part of ERM complex (Ezrin-Radixin-Moesin) that links membrane components to actin cytoskeleton, regulating cytoskeleton remodeling and cell adhesions." (PMID 27326393, 2016). "Moesin is considered an important promoter of metastasis as it has been shown to induce EMT in human mammary cell MCF10A, and there are now emerging reports that moesin is upregulated in different human cancer cell lines as well as a marker of EMT." (PMID 26983550, 2016). "Interaction of CD44 with growth factor receptors stimulates the proliferation and invasion of cancer cells; however, its interaction with ezrin/radixin/moesin proteins activates the tumor suppressor, merlin, to inhibit cancer growth." (PMID 26572077, 2015). "Here, we have studied the intracellular dynamics of PTPD1, a FERM (four-point-one, ezrin, radixin, moesin) domain-containing PTP that is over expressed in cancer cells and potentiates EGFR signalling." (PMID 25062045, 2014). "It has been recently proposed that moesin contributes to cancer cell proliferation, migration, and invasion in cancer." (PMID 24023790, 2013). "MSN connects the actin cytoskeleton and the cell membrane and is strongly up-regulated in cancers with a poor prognosis, including metastatic breast cancer, where it contributes to migratory and invasive capacity." (PMID 21501518, 2011). "Expression of proteins such as MSN that actively contribute to cell motility by promoting front-rear polarity, combined with the loss of E-cadherin (which would decrease cell-cell attachments and reduce apical-basal polarity), may significantly contribute to the invasive capacity of carcinomas." (PMID 21501518, 2011). "Other cancers instead showed an intense staining for moesin, but some had a strong expression of moesin at the cell membrane, while others showed a mixed membrane/cytoplasmic staining." (PMID 18493596, 2008). "Although our observation is only descriptive and limited to a small sample of patients, it is remarkable to find some variations in the sub-cellular localization of moesin in different cancer types." (PMID 18493596, 2008). "Some cancers showed a weak, focal expression of moesin (focal, less than 30% of the cells stain for moesin)." (PMID 18493596, 2008).
cancer (continued). "Importantly, our study reveals a mechanistically novel role for MSN as a scaffolding partner that facilitates pSTAT3 nuclear translocation and activates downstream transcription of cancer stemness-related genes." (PMID 40696387, 2025). "Moesin has been shown to be involved in cell invasion and metastasis in various malignant tumors." (PMID 38267973, 2024). "Further, we performed long-term colony formation assay to assess whether FBXW2 controls cancer cell proliferation through monitoring expression levels of Moesin." (PMID 37736741, 2023). "We then speculated that SKP2 might also protect Moesin from proteasomal degradation by FBXW2 to facilitate cancer progression." (PMID 37736741, 2023). "Deregulation of Moesin leads to several pathological conditions, including cancer." (PMID 37736741, 2023). "It has been found that aggressive malignant tumors harbour Moesin (MSN) molecule." (PMID 35531253, 2022). "As a general feature, the expression of epithelial genes (e.g. TJP3, TSPAN13, CLDN7 and EPCAM) was positively correlated with the expression of AGR2/3 and the expression of mesenchymal genes (e.g. VIM and MSN) was negatively correlated, with specific correlations according to cancer type." (PMID 35857928, 2022). "Accumulating evidence indicates that MSN plays a key role in the EMT of various malignant tumors." (PMID 36430344, 2022). "This suggests that in different cancers, the role of moesin may be different, research on different cancer models is conducive to the formulation of personalized clinical treatment plans." (PMID 33838692, 2021). "The roles of moesin may be cancer type-specific or also differ in cancer subtypes, while deimination of moesin may also play roles, and this will require further investigation." (PMID 33573274, 2021). "Further studies have shown that moesin may enhance the infiltration of immune lymphocytes in cancer by regulating a variety of inflammatory molecules, thereby improving the prognosis of LUAD patients." (PMID 33838692, 2021). "While PAD2 inhibitor followed by PAD3 inhibitor had the most effects on reducing cancer cell invasion, elevating moesin expression, and modulating EV signatures in the PDAC cells in the current study, PAD4 inhibitor had negligible effects and pan-PAD inhibitor Cl-amidine was also less effective." (PMID 33573274, 2021). "Moesin is a protein encoded by the MSN gene at chromosome location Xq12 as a member of the ERM (ezrin, radixin, and moesin) family and is known to be associated with an aggressive phenotype in several malignant tumors." (PMID 32326232, 2020). "Dynamic rearrangement of the cytoskeleton is crucial to cell mobility and migration in metastasis, and ezrin, radixin, and moesin are important membrane-cytoskeletal crosslinkers which are suggested to play vital roles in cancer progression, especially ezrin and moesin." (PMID 33072782, 2020). "Both CD93 and Moesin (MSN) are involved in apoptosis and retained in the sensitivity profile in line with theory and ANP32E that removes histone H2A.Z, a splice variant of a histone, is involved in several cancer types." (PMID 29566065, 2018). "Among them, we selected the actin-binding protein gene ANLN because our past studies showed that several actin-binding protein genes (CORO1C, FSCN1,LASP1 and MSN) were overexpressed in cancer tissues and were deeply involved in promoting human cancer cell migration and invasion." (PMID 28881803, 2017). "Six proteins 60Sacidic ribosomal protein P2, Peroxiredoxin-2, Annexin A5, PDZ and LIM domain protein 1, Src substrate cortactin and Moesin were found as emerging proteins of the H22 cell incubated with high dose lentinan which related to cancer promotion closely." (PMID 29221118, 2017). "Apart from the mutation in MSH6, two further mutations in genes known to be mutated in cancer, but rarely in biliary tract carcinoma (PTPRC, MSN), were identified as “mutations of unknown relevance”." (PMID 28146430, 2017).
cancer (continued). "Moesin has also been proposed as key regulator of metastasis in aggressive cancers." (PMID 24720764, 2014). "Of note, ezrin as well as moesin can mediate the activation of ERK pathway in cancer cells." (PMID 25136657, 2014). "Moesin was found expressed predominantly in the cytoplasm of normal and cancer cells." (PMID 20429915, 2010). "Our findings suggest that MS17 upregulated HSPPA9, LCP1 and MSN and downregulated TALDO1 in SW620 cells, which could affect the JAK-STAT signaling pathway and associated with apoptosis, proliferation, and immune response, resulting in anti-cancer effects." (PMID 38542474, 2024). "However, the biological significance of AKT-mediated Moesin phosphorylation at T558 in cancer is still unknown." (PMID 37736741, 2023). "Moreover, MSN is involved in invasion, migration, and drug resistance in different types of cancer." (PMID 37446127, 2023). "Furthermore, KLK4–7 regulate gene expression of other cancer-related factors: simultaneous overexpression of these four KLKs lead, e.g., to a distinct up-regulation of moesin and keratin 19 mRNA and protein expression, while keratin 7 is strongly down-regulated." (PMID 31307411, 2019). "Moreover, other members of ERM family, such as ezrin, function similarly as moesin in cancer cells." (PMID 20429915, 2010). "Proteins of the ezrin, radixin, and moesin (ERM) family are key regulators of cell morphogenesis and essential determinants of cancer cell metastasis." (PMID 41844278, 2026). "Lastly, we examined the impact of the expression of ENO1, MSN, Mtdh, and PABPC1 on the survival rate of cancer patients." (PMID 36923539, 2023). "Growing evidence has shown that moesin (MSN) plays a crucial role in invasion by cytoskeletal reorganization and EMT in various malignant tumors." (PMID 32326232, 2020). "It is well known that ERM complex (Ezrin, Radixin and Moesin) are cytoskeletal molecules connected to CD44 C-terminal domain and are believed to be closely related to cancer malignancy." (PMID 33292278, 2020). "Overexpression of CD44 has been observed in many types of cancer, and the interaction between CD44 and ezrin, radixin, and moesin links the actin cytoskeleton to the plasma membrane and the extracellular matrix." (PMID 32679746, 2020). "Moesin, a member of the ERM family, is not only correlated with cancer progression, but also plays a key role in HIV infection." (PMID 29085362, 2017). "Some of the other identified targets of miR-200c include Moesin (MSN), Fibronectin 1 (FN1), and Rho GTPase activating protein 19 (ARHGAP19), important regulators of the migratory and invasive capacity of cancer cells." (PMID 26283969, 2015). "To date, several more ALK hybrid proteins have been identified in various cancer types, such as TRK-fused gene (TFG)-ALK, tropomyosin 3 (TPM3)-ALK, tropomyosin 4 (TPM4)-ALK, clathrin heavy chain-like 1 (CLTCL1)-ALK, and moesin (MSN)-ALK." (PMID 23667670, 2013). "Furthermore, MSN interacts with BRCA1, colocalizing with F-actin at the plasma membrane of cancer cells." (PMID 40429863, 2025). "Along with the functions of MSN as a phosphate messenger between LPAR1 and GTPase, we found additional novel features of MSN as an intracellular transporter that transports STAT3 into the nuclei of TNBC cells, which is crucial for the transcription of specific genes in cancer." (PMID 40696387, 2025). "Then, through a comprehensive analysis of the Cancer Cell Line Encyclopedia (CCLE) and Genomics of Drug Sensitivity in Cancer (GDSC) databases, we identified GNE‐317, a PI3K/mTOR inhibitor that crosses the blood‐brain barrier and specifically targets Moesin." (PMID 39921260, 2025). "Even though a variety of immunoregulatory proteins were detected in cancer cell EMD-CM using LC-MS analyses, such as enolase, moesin, and S5A, neutralization experiments revealed that Hsp70 appeared to be the only species with a potent MΦ differentiation ability under these assays’ conditions." (PMID 39941817, 2025).
cancer (continued). "In addition, we found a highly significant inverse correlation between moesin expression and HER2 status in primary tumors of different cancers, including breast, cervix, stomach, bladder, pancreas, colon, ovary, and kidney." (PMID 36912768, 2023). "In future, it would be interesting to understand the molecular pathways involved in attenuation of FBXW2 in cancer, which could be explored to restore the expression levels of FBXW2 to limit the Moesin expression levels." (PMID 37736741, 2023). "Notably, proteins enriched in CM included Moesin (MSN), Enolase 1 (ENO1), and polyA-binding protein 1 (PABPC1), which are considered tumorigenic in many types of cancer." (PMID 36923539, 2023). "Importantly, Hsp90ab1 immuno-precipitated latent TGFβ and inactivated TGFβ, whereas MSN interacted with CD44, a cancer stem-cell marker, as well as fibronectin 1, an ECM protein." (PMID 34976221, 2022). "A specific study pointed out that when rituximab blocks CD20, moesin will be selectively recruited to the CD20 cap, leading to polarization of cancer cells, and this polarization increased the frequency of NK cells killing target cells through ADCC by 60% compared with the non-polarization." (PMID 33838692, 2021). "And the 6 molecules can also enhance the infiltration for a variety of immune lymphocytes like moesin, but there is no report on how moesin with the 6 molecules enhance the degree of immune lymphocyte infiltration in cancer." (PMID 33838692, 2021). "Within this pathway, cell migration of breast cancer cells is prevented by RA through the regulation of the expression of Moesin and the downstream inhibition of Src, FAK, and paxillin activity, providing novel mechanistic clues for the development of new drugs for cancer treatment." (PMID 28214467, 2017). "Moesin seems also to be an important promoter of epithelial–mesenchymal transition (EMT) in human mammary cell MCF10A, and it is highly expressed in a variety of human cancers and cancer cell lines." (PMID 27746764, 2016). "Our RNA-Seq data shows that expression of FN1, MSN and MMP9, which belongs to “Proteoglycans in cancer” gene list and are targets of down-regulated miRNAs, was up-regulated in 10 of 13 tissue samples (on average, 6.83, 2.43 and 21.89 folds, respectively, compared to adjacent normal)." (PMID 25126847, 2014). "These evidences suggest that Moesin might function as an upstream regulator to stabilize these oncoproteins (including SKP2), aggravate cancer progression and correlate with poor patient prognosis, and therefore could serve as a potential target for cancer therapy." (PMID 37736741, 2023). "MSN was significantly higher expressed in primary tumors of peritoneal metastasis patients and CMS4 primary CRCs, indicating that MSN expression is not increased in peritoneal lesions but already present in the primary cancers from which the peritoneal metastases derive." (PMID 35927254, 2022). "Further, we suggested that p-Moesin but not Moesin is overexpressed in primary BrCas and may be useful in future targeted cancer therapy." (PMID 33292278, 2020). "On this line, the vitamin A derivative retinoic acid (RA), frequently used in cancer therapy, has been shown to induce Src/FAK/PI3K complex signaling to cell attachment, migration, and invasion mediated by the rapid activation of the actin-binding protein moesin." (PMID 28214467, 2017). "However, ER− tumors showed a statistically significant difference vs. ER+ cancers in wild-type moesin localization, having consistently no membrane-only staining while displaying a constant cytoplasmic moesin localization." (PMID 18493596, 2008). "Here, the authors suggest that the variations in malignant phenotypes between LGR5-positive cancer stem cells and LGR5-negative cells could be due to their distinct mechanical phenotypes observed in vitro, determined by the membrane to cortex attachment proteins Ezrin/Radixin/Moesin." (PMID 38637494, 2024).